CRP (C-reactive protein)
Diseases named in the same sentence as CRP in open-access papers (continued):
Sharing a sentence is not in itself a finding about the gene and the disease.
Arrhythmia (continued). "Several studies have described the increase in CRP and IL-6 levels in patients with paroxysmal and permanent AF and suggest that the presence of inflammation promotes the development or perpetuates arrhythmia." (PMID 33535417, 2021). "Among inflammatory and cardiac biomarkers, only C-reactive protein, D-dimer, and aspartate aminotransferase differed significantly between the two groups, with being more elevated among the arrhythmia group." (PMID 35070544, 2021). "Previous studies demonstrated that arrhythmias are related to proinflammatory cytokines such as interleukin 6 and C-reactive protein by the modulation of ion-channel function and aggravation of the sympathetic system." (PMID 33921213, 2021). "Another study confirmed that patients with PAF had significantly higher levels of CRP (C-reactive protein) than their controls, in a graded fashion according to arrhythmia burden." (PMID 26229966, 2015). "The levels of various inflammatory markers before ablation, including C-reactive protein (CRP), white blood cell count, and neutrophil-to-lymphocyte ratio, have been studied as potential predictors of arrhythmia recurrence after PVI, but the results are counterintuitive." (PMID 40507635, 2025). "We aimed to investigate whether early post-PVI levels of C-reactive protein (CRP), white blood cells, tumour necrosis factor alpha (TNF-α) and transforming growth factor beta 1 (TGF-ß1) are associated with long-term arrhythmia recurrence." (PMID 40507635, 2025). "However, it remains unclear whether CRP independently predicts arrhythmia onset or merely serves as a marker of systemic inflammation." (PMID 40151738, 2025). "The aim of this study was to investigate early post-PVI levels of inflammatory biomarkers, including CRP, neutrophils (Neu), leukocytes (Lkc), TNF-α and TGF-ß1, as potential predictors of arrhythmia recurrence." (PMID 40507635, 2025). "The HR, occurrence with Killip III&IV and arrhythmia, usage of IABP and ventilator, WBC, Glu, CRP, and Cr in the MACCE group were significantly higher, while the SBP, DBP, HBG, TC, and LVEF were significantly lower than those in the non-MACCE group (P < 0.05)." (PMID 37061678, 2023). "In several case-controlled studies, increased levels of inflammatory markers, such as CRP, IL-6, IL-8, and TNF, and elevated neutrophil and lymphocyte ratios have been reported in patients with arrhythmia compared with those in patients with sinus rhythm." (PMID 33796569, 2021). "Some studies suggest that elevated CRP levels before PVI may predict arrhythmia recurrence, suggesting that the suppression of inflammation may play a critical role in reducing arrhythmia episodes." (PMID 40507635, 2025). "CRP was an independent predictor of POAF and postsurgery inflammation may represent a major driver in the pathophysiology of the arrhythmia." (PMID 39139903, 2024). "Moreover, patients in the MACCE group showed a significantly higher HR, Killip class, occurrence of arrhythmia, usage of IABP and ventilator, WBC, Glu, CRP, and Cr, but lower SBP, DBP, HBG, and LVEF than those in the non-MACCE group (P < 0.05)." (PMID 37061678, 2023). "In contrast, arrhythmia, other diseases, FEV1, mean corpuscular volume, BMI, mean corpuscular hemoglobin concentration, albumin, C reactive protein, smoking duration, hematocrit, aspartate aminotransferase, percentage VC, and duration of smoking cessation were unlikely to predict rapid decliners." (PMID 37012340, 2023). "The number of arrhythmia and infectious disease patients, lactate levels, serum BUN levels, and serum CRP levels were significantly higher and the systolic blood pressure (BP) values, pH levels, and serum hemoglobin levels significantly lower in the AKI group than in the no-AKI group." (PMID 27596162, 2016). "The possible relation of heart rate and arrhythmias with CRP, Hp and cTnI was statistically studied without obtaining any significance." (PMID 22937913, 2012).
Arrhythmia (continued). "Even though, the evaluation of ECG (presence of arrhythmias and tachycardia) and vertebral heart score (VHS) was evaluated in relation to cTnI, CRP and Hp without obtaining any association." (PMID 22937913, 2012). "In cases of CRP concentrations below the detection limit, CHF needs to be considered in patients with typical clinical signs that may include tachypnea/dyspnea, cough, tachycardia, a heart murmur, a weak femoral pulse and/or arrhythmias." (PMID 29573742, 2018). "A specific use of CRP may lie with T cell therapies, namely Chimeric Antigen Receptor (CAR) T cells where daily measurements of CRP is essential to detect cytokine release storm, which may present as severe hypotension, LV dysfunction, arrhythmia and cardiac arrest." (PMID 32642841, 2020).
coronary atherosclerosis (69 papers, 2009 to 2026). Atherosclerosis of the coronary vasculature. "Studies have shown that hs-CRP levels are closely associated with the presence and severity of carotid and coronary atherosclerosis." (PMID 40356625, 2025). "Observational studies have shown strong associations between CRP levels,coronary atherosclerosis, and vascular risk." (PMID 39077721, 2022). "Previously showed that α-1-antitrypsin, 1-acid glycoprotein, ceruloplasmin and CRP are associated with the severity of coronary atherosclerosis." (PMID 36361589, 2022). "Use of the interaction term improved the prediction of coronary atherosclerosis beyond ACC/AHA 10-year risk score plus hs-CRP from C-statistic = 0.835 (95% CI 0.773, 0.896) to 0.862 (95% CI 0.807, 0.917), likelihood ratio test P < 0.001." (PMID 35732827, 2022). "A retrospective cross-sectional study also found that the TB level was negatively associated with inflammatory markers including CRP in patients with coronary atherosclerosis." (PMID 36407305, 2022). "Resistin levels were also found to be associated with plasma CRP levels in the Study of Inherited Risk of Coronary Atherosclerosis (SIRCA)." (PMID 28806778, 2017). "Plasma resistin levels are positively associated with CRP and predictive of coronary atherosclerosis in humans." (PMID 28298189, 2017). "In another study called SIRCA (Study of Inherited Risk of Coronary Atherosclerosis), circulating leptin was associated with inflammatory factors (IL-6, CRP, and TNF-α) and also represented an independent marker for coronary artery calcifications." (PMID 24616817, 2014). "The association between CRP and cardiovascular events is well established, but the possible relationship between CRP and presence of coronary atherosclerosis is less studied and has mainly focused on the degree of coronary calcification as measured by CAC score." (PMID 37500663, 2023). "In agreement with this, circulating levels of inflammatory markers such as CRP, erythrocyte sedimentation rate, and IL‐6 in RA patients are associated with a risk of cardiovascular events and with radiologic measures of coronary atherosclerosis." (PMID 35583917, 2022). "Furthermore, the impact of opium addiction on high-sensitivity CRP suggests that opium might cause accelerated multi-system chronic inflammation and coronary atherosclerosis." (PMID 34803676, 2021). "Research regarding CRP and coronary atherosclerosis in samples from the general population is sparse." (PMID 37500663, 2023). "Several studies have reported that serum TB level was inversely correlated with CRP in overweight individuals and patients with coronary atherosclerosis." (PMID 37208703, 2023). "Overall, elevated CAC and hs-CRP levels were not only indicative of advanced coronary atherosclerosis and systemic inflammation, but in their presence, comorbidities appeared to be associated with a higher risk of death." (PMID 34356982, 2021). "Studies have shown that inflammatory pathways play an important role in the development of coronary atherosclerosis and thrombosis, and that hs-CRP is a reliable biomarker of inflammation." (PMID 33028234, 2020). "Their elevation is significantly correlated with CRP concentration, and appear to be closely related to the severity of coronary atherosclerosis and to myocardial damage." (PMID 31934638, 2019). "The Air Force/Texas Coronary Atherosclerosis Prevention Study (AFCAPS/TexCAPS) CRP substudy suggested that CRP screening can be conducted to improve the targeting of statin therapy adjunctively with lipid testing." (PMID 30274193, 2018). "This study evaluates the effect of BROM-QR on homocysteine (HOMC) and high sensitive C-reactive protein (hs-CRP), the biochemical markers of coronary atherosclerosis/inflammation, in patients with uncontrolled T2DM." (PMID 27069561, 2016). "The value of fibrinogen in predicting the severity of coronary atherosclerosis was even superior to that of hs-CRP and WBCC." (PMID 25426943, 2014).
coronary atherosclerosis (continued). "Inflammation plays a pivotal role in the pathogenesis of coronary atherosclerosis and cardiovascular disease, and markers of inflammation such as C-reactive protein (CRP) have been shown to be good predictors of future cardiovascular events." (PMID 22347630, 2011). "CRP > 10 mg/L was reported in less than 5% of the population in a large cohort (n = 22,403) of men and women from the Women’s Health Study, Women’s Health Initiative, Air Force/Texas Coronary Atherosclerosis Prevention Study and the Physician’s Health Study." (PMID 36575541, 2022). "The decrease was paralleled by declines in C-reactive protein, indicating that the contrast-enhanced cardiac magnetic resonance offers the potential to indirectly visualize the transient inflammatory process in coronary artery atherosclerosis by characterizing the changes in plaque enhancement." (PMID 32849214, 2020). "Similar to the role of C-reactive protein (CRP), ALP has been reported as a novel risk marker (inflammatory mediator) for cardiovascular disease with a proven association between elevated serum ALP levels and coronary atherosclerosis." (PMID 29973151, 2018). "However, the results persisted even after adjustments for CRP, which indicated that RDW may be associated with coronary atherosclerosis through other pathways besides inflammation." (PMID 34814760, 2022). "Moreover, the elevated serum levels of C-reactive protein (CRP) and interleukin (IL)-6 are detectable in CVD patients 11, 12, suggesting systemic inflammatory responses accompanying the progression of coronary atherosclerosis." (PMID 36185605, 2022). "The levels of resistin were compared to inflammatory markers and were prognostic of coronary atherosclerosis, independent of CRP." (PMID 34745775, 2021). "In rabbits transgenic for human CRP also, CRP did not affect aortic or coronary atherosclerosis lesion formation." (PMID 24948846, 2014). "In a prospective study of 361 patients, the role of leptin as an independent predictor of cardiovascular events in patients with angiographically confirmed coronary atherosclerosis was postulated, without being influenced by the lipid profile or C-reactive protein (CRP)." (PMID 38541144, 2024). "Based on this observation, it is possible that the biological consequence of CRP- and TNF-α-induced PAPP-A expression in human PBMCs was enhanced IGF-I bioactivity mediated by PAPP-A proteolysis of IGFBP-4, thus contributing to the progression of both coronary atherosclerosis and restenosis." (PMID 22997483, 2012). "Therefore, the underlying mechanism assessing the association of the level of CRP, the severity of NAFLD, and subclinical coronary atherosclerosis could not be addressed in this study." (PMID 34011282, 2021).
esophageal cancer (69 papers, 2009 to 2026). A primary or metastatic malignant neoplasm involving the esophagus. "The present study examined the association between postoperative CRP levels and AL in patients who underwent surgery for esophageal cancer." (PMID 37964057, 2023). "Systemic inflammation following radiotherapy has been associated with transient cardiac dysfunction including HF and elevated pre-treatment serum CRP levels have been associated with poorer prognosis in esophageal cancer patients." (PMID 32154028, 2020). "CRP is a protein of acute phase inflammation and has been reported to be associated with prognosis in esophageal cancer patients (Nozoe, Saeki & Sugimachi, 2001)." (PMID 30258731, 2018). "In addition, we also observed positive linear associations for cancers of esophagus and stomach along with the increase of CRP concentration (FDR-adjusted Poverall < 0.050, and FDR-adjusted Pnon-linear > 0.050)." (PMID 36117174, 2022). "In addition, some recent studies have demonstrated that the CRP/Alb ratio is a promising inflammation-associated prognostic factor in cancer, including liver, lung, gastric, and esophageal cancer." (PMID 27344157, 2016). "This study aimed to evaluate its usefulness in determining anastomotic leakage after esophagectomy for esophageal cancer compared with C-reactive protein (CRP), white blood cells (WBC), and neutrophils (Neut)." (PMID 39906219, 2025). "Presepsin levels on PODs 5 and 7 after esophagectomy for esophageal cancer are valuable biomarkers for the early detection of anastomotic leakage compared to other inflammatory biomarkers such as CRP, WBCs, and Neuts." (PMID 39906219, 2025). "The primary aim of this study was to determine the accuracy and optimal cut-off values of CRP with regard to anastomotic leakage in esophageal cancer patients following minimally invasive esophagectomy." (PMID 37103558, 2023). "Recently, a C-reactive protein (CRP)-based modified geriatric nutrition risk index (mGNRI) was developed and proved to be an effective tool for predicting the clinical outcome of esophageal cancer." (PMID 35433784, 2022). "The C-reactive protein–ALB ratio before treatment can be used as a potential prognostic biomarker in patients with head and neck cancer, esophageal cancer, and bile duct cancer; an elevated C-reactive protein–ALB ratio predicts a poorer prognosis." (PMID 36428725, 2022). "The Glasgow Prognostic Score, which uses CRP and albumin, is one such example validated for colorectal and esophageal cancer." (PMID 33054830, 2020). "In recent years, the role of pre-treatment C-reactive protein/albumin ratio (CAR) in prognosis of esophageal cancer (EC) has been investigated by several studies." (PMID 31783812, 2019). "In recent work, CRP/PNI showed a prognostic ability in esophageal cancer patients and fracture surgery patients." (PMID 31312573, 2019). "We analyzed patients who underwent esophageal cancer surgery and found that a higher preoperative level of d-ROMs was closely associated with delay in postoperative normalization of WBC count and CRP level." (PMID 30461602, 2018). "A previous meta-analysis demonstrated that the high level of serum C-reactive protein were significantly correlated with poor overall survival in esophageal cancer patients." (PMID 27978831, 2016). "Among these indicators, the CRP/Alb ratio has been reported as a novel reliable marker in different cancers such as lung, liver, gastric, and esophageal cancer." (PMID 27344157, 2016). "The following search terms were used: ("esophageal cancer" OR "esophageal carcinoma" OR "esophageal neoplasm" OR "oesophageal cancer") AND ("C-reactive protein-albumin-lymphocyte" OR "CALLY" OR "CRP-albumin-lymphocyte") AND ("survival" OR "prognosis" OR "mortality" OR "outcome")." (PMID 41179090, 2025).
esophageal cancer (continued). "Retrospective studies indicated that baseline nutrition- and inflammation-related markers—such as high prealbumin, reduced CRP, and favorable indices such as PNI—were strongly linked to improved progression-free survival in advanced esophageal cancer patients receivingPD-1 blockade and chemotherapy." (PMID 41402954, 2025). "For instance, in esophageal cancer patients, the level of C-reactive protein indicates prognosis." (PMID 38504280, 2024). "Haptoglobin and C-reactive protein (CRP) belong to the acute phase proteins and increased serum concentrations can be found in inflammation, injury, infections and various malignant diseases including esophageal cancer." (PMID 38254757, 2024). "Importantly, a SNP CRP has been reported to be a determinant of serum CRP levels after major esophagectomy for thoracic esophageal cancer." (PMID 37873776, 2023). "Early changes in postoperative CRP levels may help to detect AL early following esophageal cancer surgery." (PMID 37964057, 2023). "In conclusion, very early postoperative changes in CRP may be useful in identifying AL following esophageal cancer surgery." (PMID 37964057, 2023). "Furthermore, with the ZJ test cohort, this study identified several other prognostic factors including tumor differentiation, T stage, N stage, CEA and CRP, which were well-established in previous studies regarding esophageal cancer." (PMID 36557010, 2022). "Several studies reported that the high level of CRP as an independent prognostic factor was connected with OS in gastric, lung, ovarian, and esophageal cancers, and the high preoperative or postoperative CRP levels were related to worse survival prognosis in ESCC patients." (PMID 35965555, 2022). "Consistent with previous results in esophageal cancer, our data show that the CRP/PNI ratio could be a predictor of laryngeal cancer." (PMID 31312573, 2019). "A high CRP level ≥ 4.0 mg/dl on POD 4 may predict SICs in esophageal cancer patients who received neoadjuvant chemotherapy followed by curative resection with perioperative steroid therapy and ERAS care." (PMID 29202716, 2017). "CRP value on POD 4 may be useful for predicting SICs in esophageal cancer patients who receive radical esophagectomy with perioperative steroid therapy and ERAS care." (PMID 29202716, 2017). "Therefore, for patients with esophageal cancer with high CRP, whether nutritional support can be given in advance to improve the prognosis and survival of patients remains to be further explored." (PMID 39070256, 2024). "Furthermore, these studies indicate the predicative potential of postoperative serum CRP level, and the combination of preoperative and postoperative CRP may improve OS prediction in esophageal cancer patients." (PMID 31533862, 2019). "The aim of this study was to assess whether early changes in the serum CRP can be used to predict ICs in advanced esophageal cancer patients who received esophagectomy and two- or three-field lymph node dissection with perioperative steroid therapy and ERAS care." (PMID 29202716, 2017). "However, inflammation and C-reactive protein (CRP) levels are not always elevated in esophageal cancer patients, leaving CRP insufficient for high-risk stratification." (PMID 27517497, 2016). "However, raised CRP concentrations have been demonstrated to be an indicator of a poorer prognosis for squamous cell carcinoma (SCC) in patients with esophageal cancer, but concerning the cancer of the oral cavity only a very few studies have dealt with this topic so far." (PMID 20673375, 2010). "The NUn score, which integrates CRP, ALB, and WBC values, was initially developed to predict anastomotic leakage in esophageal cancer." (PMID 40299490, 2025).